EFNA1 (ephrin A1)
Diseases named in the same sentence as EFNA1 in open-access papers (continued):
Sharing a sentence is not in itself a finding about the gene and the disease.
gastric cancer (continued). "Next, we examined whether binding of Ephrin A1-Fc to surfaces of gastric cancer cells was affected by C1GALT1." (PMID 32005975, 2020). "Likewise, ephrin A1-Fc increases EphA2 phosphorylation, decreases EphA2 protein expression, and inhibits growth in gastric cancer cells." (PMID 32811512, 2020). "Ephrin A1 binds to and activates EGFR to induce epithelial-mesenchymal transition (EMT) and promote metastasis of gastric cancer cells." (PMID 39838173, 2025). "To further address the clinical relevance between Ephrin A1 expression level and EGFR phosphorylation level in gastric cancer patients, we performed a human gastric tumor tissue array analysis." (PMID 39838173, 2025). "However, the exact mechanism of Ephrin A1 in gastric cancer metastasis remains largely unknown." (PMID 39838173, 2025). "Interestingly, NCI-N87 cells overexpressing Ephrin A1 appeared morphological changes, which were loss of tightly clustered features and appearance of elongated mesenchymal features (Fig. EV1B), implying the epithelial-mesenchymal transition (EMT) in gastric cancer cells." (PMID 39838173, 2025). "Together, these results demonstrate that the functions of Ephrin A1 in inducing EMT and metastasis of gastric cancer cells are EphA2 receptor independent." (PMID 39838173, 2025). "Ephrin A1 further induced EMT and facilitated invasion, transendothelial migration, colonization and metastasis capacities of gastric cancer cells." (PMID 39838173, 2025). "This study identifies Ephrin A1 as a functional EGFR ligand, activating EGFR signaling, epithelial-mesenchymal transition (EMT) and malignant invasion in gastric cancer." (PMID 39838173, 2025). "In gastric cancer, C1GALT1 promotes EPHA2 phosphorylation and enhances soluble Ephrin A1-mediated migration mainly by modifying the O-glycosylation of EPHA2, thereby affecting the cell invasiveness of gastric cancer cells." (PMID 38699634, 2024). "The expression of EFNA1 (p = 1.62E-12), EFNA3 (p = 4.17E-07), and EFNA4 (p = 1.62E-12) were significantly increased in gastric cancer tissues." (PMID 35309935, 2022). "EFNA1 is a transmembrane protein, and EFNA11 expression is upregulated in a number of tumor cells, including gastric cancer, colorectal cancer, and hepatocellular cancer." (PMID 34337075, 2021). "To explore the mechanism of Ephrin A1 in promoting gastric cancer metastasis, we detected the expression of Ephrin A1 in different gastric cancer cell lines and found that NCI-N87 and AGS cells had low expression levels of Ephrin A1 and MKN45 cells were highly expressed of Ephrin A1 (Fig. EV1A)." (PMID 39838173, 2025). "Interestingly, we uncovered that Ephrin A1 induced EMT of gastric cancer cells by activating EGFR signaling to promote metastatic capacities, which provides a new mechanistic insight for gastric cancer metastasis." (PMID 39838173, 2025). "Compared with normal adjacent tissues, EFNA1, EFNA3, and EFNA4 were up-regulated in gastric cancer." (PMID 35309935, 2022). "Ephrin A1 is the ligand for EPHA receptors and is overexpressed in gastric cancer." (PMID 32005975, 2020).
hepatocellular carcinoma (12 papers, 2010 to 2025). A malignant tumor that arises from hepatocytes. "It was reported that ephrin-A1 was found by a dot blot assay using serum derived from hepatocellular carcinoma patients." (PMID 33804570, 2021). "Analysis of clinical samples has demonstrated that up-regulation of ephrin-A1 is positively correlated with a poor prognosis in hepatocellular carcinoma and colon cancer." (PMID 33804570, 2021). "In keeping with our finding, ephrin-A1 has also been detected in the serum of patients with liver carcinoma." (PMID 24040255, 2013). "EFNA1 was overexpressed in hepatocellular carcinoma and can inhibit growth of malignant mesothelioma by phosphorylating EPHA2." (PMID 23158542, 2012). "In addition, EFNA1 was detected in the supernatant of most of the authentic Hepatocellular carcinoma (HCC) cell lines, and elevated serum EFNA1 levels were noted for HCC patients by comparing to the patients with liver cirrhosis." (PMID 38987376, 2024). "In addition, EFNA1 expression is upregulated in gastric cancer, oesophageal squamous cell carcinoma, hepatocellular carcinoma, cervical cancer and ovarian cancer and is positively correlated with a poor prognosis." (PMID 34344926, 2021). "Indeed the recent finding that EFNA1 is found in the serum of patients with hepatocellular carcinoma, suggests that soluble EFNA1 is also relevant for in situ cancer." (PMID 20979646, 2010). "EFNA1-induced EphA1 activation promotes SDF-1 secretion and endothelial progenitor cell chemotaxis to hepatocellular carcinoma through the SDF-1/CXCR4 signalling pathway." (PMID 34344926, 2021).
glioma (10 papers, 2015 to 2025). A benign or malignant brain and spinal cord tumor that arises from glial cells (astrocytes, oligodendrocytes, ependymal cells). "In low-grade gliomas, higher ephrin-A1 levels are associated with increased infiltration of CD4+ T cells, myeloid dendritic cells, and neutrophils." (PMID 41200151, 2025). "Ephrin-A1 expression is significantly downregulated in glioma cell lines and primary gliomas compared to normal brain tissue." (PMID 41200151, 2025). "In U251 glioma cells, forced expression of ephrin-A1 significantly inhibited migration, proliferation, and anchorage-independent growth." (PMID 41200151, 2025). "Conversely, ephrin-A1 and ephrin-A5 exhibit tumor-suppressive properties by promoting receptor internalization and degradation, thereby inhibiting glioma cell proliferation and migration." (PMID 41200151, 2025). "The high-affinity EphA2 ligand, ephrin-A1, is expressed at a low level in EphA2 positive areas in glioma." (PMID 35448036, 2022). "As shown, ephrin A1 stimulated Src phosphorylation in the indicated glioma cell lines, congruous with prior reports documenting src activation in response to ligand." (PMID 29290990, 2017). "Elevated ephrin-A1 expression may lead to a less aggressive phenotype in differentiated glioma cells." (PMID 35448036, 2022). "Ephrin-A1 expression was associated with lower grade gliomas, while patients with tumors positive for EPHA2 and negative for ephrin-A1 exhibited shorter OS and PFS." (PMID 34445116, 2021). "Hypermethylation at CpG islands of promoter regions of many ephrins, including EfnA5, and Eph receptors have been demonstrated in acute lymphoblastic leukaemia and miRNAs, such as miR-210 and miR-26b, have been shown to downregulate the expression of EfnA1 in hepatic ischaemia and EphA2 in gliomas." (PMID 31988455, 2020). "Furthermore, binding of Ephrin A1 to EphA2 has in prostate cancer and glioma cells been demonstrated to block proliferation- and invasion signaling mediated by EphA2, an effect in part caused by inhibition of EphA2 Ser897 phosphorylation." (PMID 27533087, 2016). "In addition, infiltrative invasion of glioma stem cells expressing EphA2 in vivo, which is completely independent of ephrin-A1, A3 and A4 ligands, was disrupted by S897A mutation." (PMID 26158630, 2015). "It has been known that EFNA1 is a major cognate ligand of EPHA2 in vivo, but the function of EFNA1 is thought to impair EPHA2 activity in glioma cells, which promoted us to investigate the difference of PDGFA/EPHA2 axis and EFNA1/EPHA2 axis." (PMID 35105853, 2022). "Overexpression of ephrin-A1 downregulates EphA2 and FAK, leading to reduced migration, adhesion, and proliferation of glioma cells." (PMID 35448036, 2022). "Previous research revealed that EphA2-positive with EFNA1-negative glioma patients had shorter OS and PFS." (PMID 35945523, 2022).
prostate carcinoma (9 papers, 2015 to 2022). A carcinoma that arises from epithelial cells of the prostate gland. "In agreement, UniPR129 was shown to inhibit ephrin A1-Fc-associated prostate cancer cell cytotoxicity and angiogenesis in vitro." (PMID 32811512, 2020). "UniPR126 was shown to disrupt the EphA2-ephrin A1 complex and to inhibit EphA2 phosphorylation in prostate cancer cells at a level 6-fold higher (pIC50 = 4.89)." (PMID 32811512, 2020). "Further functional assays revealed that LCA inhibits EphA2 autophosphorylation and blocks ephrin A1-related prostate cancer cell cytotoxicity." (PMID 32811512, 2020). "SNPs in the region of EFNA1, DPM3 and KRTCAP3 have previously been associated with prostate cancer risk and γ-glutamyl transferase (GGT), an indicator of liver disease." (PMID 29659830, 2018). "Exposed to ephrin-A1 PC3 prostate cancer cells alter adhesion to extracellular matrix (ECM) proteins." (PMID 25644492, 2015). "However, LCA by targeting EphA2 LBD, is able to hamper receptor autophosphorylation induced by stimulation by ephrin A1-Fc in human prostate cancer cells and colon adenocarcinoma cell lines (PC3 and HT29) and avoids rounding and retraction of PC3 cells caused by EphA2 activation." (PMID 36142306, 2022). "Interestingly, recent work suggest that EphA2-ephrin-A1 signaling may support cell migration and invasion in prostate cancer and melanoma cells in this manner." (PMID 27246245, 2016). "Our finding that ephrin-A1 attached to a surface stimulates PC3 cells to crosstalk (signaling pathways) with integrins containing β1-subunits hints at a possible mechanism by which PC3 prostate cancer cells preferably metastasize in bone, whose major ECM protein is collagen I." (PMID 25644492, 2015). "It was reported that in response to soluble ephrin-A1 PC3 cells, a prostate cancer cell line, lower adhesion to fibronectin and round up32." (PMID 25644492, 2015). "In light of the decreased migration of prostate cancer cells upon stimulation of EphA2 with ephrin-A1, downregulation of ephrin-A1 in aggressive prostate cancers is not surprising." (PMID 29682554, 2018). "However, the effect of ephrin-A1 on EphA2 expressing cells may also be cell type-specific and transformation status-dependent: for instance, ephrin-A1 treatment inhibited proliferation of prostate cancer cells but failed to do so in fibroblasts." (PMID 33572284, 2021).
colorectal cancer (8 papers, 2021 to 2026). A primary or metastatic malignant neoplasm that affects the colon or rectum. "In conclusion, the analysis reveals a significant association between the genetic variants RASSF1 (rs2073498), SERPINE1 (rs1799889), and EFNA1 (rs12904) and colorectal cancer, highlighting their potential as valuable genetic markers." (PMID 40004552, 2025). "This study identifies specific genetic variants (RASSF1 rs2073498, SERPINE1 rs1799889, and EFNA1 rs12904) associated with colorectal cancer in the Mexican population and highlights their value as potential biomarkers for late-stage prognosis." (PMID 40004552, 2025). "For example, higher ephrin-A1 expression in liver and colorectal cancer is associated with a worse prognosis, but in stage I non-small cell lung cancer patients, higher expression levels of EphA2 and ephrin-A1 improved their prognosis." (PMID 36232447, 2022). "Studies have confirmed that EFNA1 may be associated with the prognosis of colorectal cancer, and single nucleotide polymorphism is the main factor leading to genetic susceptibility to tumors." (PMID 34399788, 2021). "EphA2 and ephrin-A1 increase was also more prevalent in the initial phase of cancer development as compared to the later phase, and ephrin-A1 overexpression promoted the proliferation of HT29 colorectal cancer cells." (PMID 36830852, 2023). "The EFNA1-Linifanib combination may represent a potential therapeutic approach to mitigate anti-angiogenic resistance and restrain metastatic progression in colorectal carcinoma." (PMID 41542227, 2026). "In HCAE cells, overexpressed genes included EFNA1 and LIF, two genes commonly upregulated in colorectal cancer and associated with poor patient outcomes, and PTGS2 (COX2), a gene associated with the protective effect of aspirin in the colorectal cancer setting." (PMID 34700376, 2021). "PCK1 and EFNA1 have been found to be involved in important life activities such as cell proliferation and apoptosis, tumor angiogenesis, malignant cell events, and invasiveness, and their expression is upregulated in a variety of tumors [such as colorectal cancer]." (PMID 35910380, 2022).
melanoma (7 papers, 2005 to 2023). A malignant, usually aggressive tumor composed of atypical, neoplastic melanocytes. "In addition, high expression of its ligand, ephrin-A1, was also correlated with increased melanoma thickness, as well as decreased patient survival." (PMID 34445116, 2021).
ovarian carcinoma (7 papers, 2006 to 2025). A malignant neoplasm originating from the surface ovarian epithelium. "Interestingly, previous studies revealed that the high expression of ABCA1, APLP2, C3, EPHA2, and EFNA1 were associated with poor prognosis and epithelial ovarian cancer progression." (PMID 39135097, 2024). "In a proof-of-concept study, magnetic NPs (MNPs) functionalized with ephrin-A1 mimetic peptides removed ovarian cancer cells overexpressing the EphA2 receptor from peritoneal fluid in a murine model of ovarian cancer." (PMID 30366428, 2018). "EphA1 and EphA2 over-expression was correlated with ephrin A1 suggesting that their interaction may have a role in ovarian cancer progression." (PMID 16737551, 2006). "Initially, the expression of 20 different Eph and ephrin genes (EphA1-A8, EphB1-4 and 6, ephrin A1-5 and ephrin B1-2) were screened by quantitative real time reverse transcriptase polymerase chain reaction (Q-PCR) on two normal ovaries and ten ovarian cancer specimens." (PMID 16737551, 2006). "Similar to ovarian cancer, miR-192 treatment mediated a robust downregulation of EGR1 and HOXB9 levels and significant decreases in several angiogenic factors including IL6, IL8 and EFNA1; consistent with the pattern observed after siEGR1/siHOXB9 treatment." (PMID 27041221, 2016). "There are many cancers and cancer cell lines that overexpress both EPHA2 and EFNA1, including bladder and ovarian cancer, which indicates that EFNA1 expression does not always lead to EPHA2 downregulation." (PMID 20979646, 2010).
cervical carcinoma (6 papers, 2010 to 2025). A carcinoma arising from either the exocervical squamous epithelium or the endocervical glandular epithelium. "Recent studies have shown that EFNA1 overexpression serves as an independent prognostic risk factor in cervical cancer, demonstrating robust predictive value for survival outcomes." (PMID 40406253, 2025). "EFNA1 mutation occurred in 2.5% of cervical cancer patients." (PMID 32300605, 2020). "EFNA1, a tumour-related gene, was significantly upregulated in numerous tumours, including cervical cancer." (PMID 32300605, 2020). "EFNA1 expression was reported to be related to deep invasion, parametrial invasion, tumour size, and outcome in cervical carcinoma." (PMID 32300605, 2020). "Our study also observed the high expression of EFNA1 in cervical cancer, and its expression was related to poor overall survival." (PMID 32300605, 2020). "To investigate the role of key genes in cervical cancer survival prognosis, we comprehensively analyzed the correlation between the expression levels of EFNA1, CXCL8, and PPP1R14A, and various clinical features, including age, stage, tumor grade (T), lymph node status (N), and metastasis status (M)." (PMID 40406253, 2025). "The prognostic values of SPP1, EFNA1, and MMP-1 in cervical cancer have been investigated in previous studies." (PMID 32300605, 2020). "To examine the role of endogenous soluble and membrane bound EFNA1 in the context of EPHA2 oncogenesis, we chose HeLa cells, an aggressive cervical cancer cell line that expresses both EPHA2 and EFNA1." (PMID 20979646, 2010). "The ability of SM to inversely down-regulate EFNA1 and TFRC and up-regulate HIST1H2BK and ISG20 could illustrate a probable importance of these genes in SM-induced inhibition of growth of cervical carcinoma cells." (PMID 31523389, 2019).
esophageal cancer (6 papers, 2020 to 2025). A primary or metastatic malignant neoplasm involving the esophagus. "EFNA1 was highly expressed in esophageal cancer and significantly associated with poor prognosis." (PMID 37160815, 2023). "EFNA1 and its receptor EPHA2 were upregulated and linked to shorter survival in patients, and activation of the EFNA1/EPHA2 signalling pathway regulated the proliferation and metastasis of oesophageal cancer cells." (PMID 32732965, 2020). "We concluded that EFNA1 protein expression has been confirmed to be predictive to poor survival in patients with ESCA, which might be a good target for esophageal carcinoma therapy." (PMID 34399788, 2021).
malignant mesothelioma (5 papers, 2012 to 2023). A malignant neoplasm of the pleura or peritoneum, arising from mesothelial cells. "There is research evidence that EFNA1 is regulatory molecules for many malignant tumors, for example, EFNA1 induces miR-302b expression in malignant mesothelioma (MM) cells and inhibit the growth of tumor spheres by inducing apoptosis." (PMID 34399788, 2021). "Moreover in malignant mesothelioma and lung cancer, Ephrin-A1 conjugated nanoparticles of let-7a conspicuously restrain tumor development as compared to either ephrin-A1 or let-7a nanoparticle alone." (PMID 26259238, 2015).
osteosarcoma (5 papers, 2012 to 2024). A usually aggressive malignant bone-forming mesenchymal neoplasm, predominantly affecting adolescents and young adults. "Our group has previously shown that extracellular S100A4 induces the expression of ephrin-A1 and osteopontin in osteosarcoma cell lines by activating the transcription factor NF-κB." (PMID 22853000, 2012). "The metastasis-promoting protein S100A4 induces expression of ephrin-A1 and osteopontin in osteosarcoma cell lines." (PMID 22853000, 2012). "Our group has previously shown that extracellular S100A4 induces the expression of ephrin-A1 and osteopontin in osteosarcoma cell lines." (PMID 22853000, 2012). "According to their findings, the expression of ephrin-A1, a ligand with high affinity with the EPHA tyrosine kinase receptors, was found 10-fold higher in osteosarcoma cells compared to normal osteoblasts." (PMID 35563562, 2022). "In this study, we explored the role of four genes (EFNA1, P4HA1, STC2, and MAFF) profiled in a previous study on osteosarcoma." (PMID 34337075, 2021). "The interaction between EPHA2 and ephrin-A1 enhanced the phosphorylation of EPHA2′s tyrosine and increased the mitogenic process via the Ras/MAPK pathway, which eventually enhanced the proliferation and migration of SaOS2 and MNNG/HOS human osteosarcoma cells." (PMID 35563562, 2022).
esophageal squamous cell carcinoma (4 papers, 2023 to 2024). Esophageal squamous cell carcinoma (ESCC) is a type of esophageal carcinoma (EC) that can affect any part of the esophagus, but is usually located in the upper or middle third. "Ephrin A1 (EFNA1) is upregulated in esophageal squamous cell carcinoma (ESCC) with pulmonary metastasis and correlates with poor prognosis, meanwhile EA1 aptamer exhibits robust binding to ESCC cells with remarkable specificity." (PMID 38704694, 2024). "We previously identified that serum EFNA1 and MMP13 were potential biomarker for early detection of esophageal squamous cell carcinoma." (PMID 38987376, 2024).